HNF1A (HNF1 homeobox A)
Diseases named in the same sentence as HNF1A in open-access papers (continued):
Sharing a sentence is not in itself a finding about the gene and the disease.
diabetes (continued). "In total, 615 autoantibody-negative participants among 4712 cases of paediatric diabetes underwent genetic sequencing, revealing 19 with HNF1A variants." (PMID 37798422, 2023). "Indeed, adolescents in families with HNF1A diabetes preferred testing in adolescence when parents and their children can engage in joint decision-making regarding genetic testing." (PMID 37794142, 2023). "We previously performed a systematic screening of the Norwegian Childhood Diabetes Registry (NCDR), which covers >99% of paediatric diabetes cases in Norway, to identify carriers of HNF1A variants in autoantibody-negative children." (PMID 37798422, 2023). "HNF1A variants were associated with an earlier age of diabetes diagnosis in the Hispanic-Latino population, but not in the other populations." (PMID 36216889, 2023). "We extended our previous screening of the Norwegian Childhood Diabetes Registry by 830 additional samples and comprehensively genotyped HNF1A variants in autoantibody-negative participants using next-generation sequencing." (PMID 37798422, 2023). "Short hairpin RNA–mediated (shRNA-mediated) suppression of HNF1A in primary human pseudoislets led to blunted insulin output and dysregulated glucagon secretion after transplantation in mice, recapitulating phenotypes observed in patients with diabetes." (PMID 37943614, 2023). "First, this approach improves discovery by screening for HNF1A-MODY in high-risk populations and, second, it combines clinical and functional investigations into a robust classification scheme that increases precision in diagnosing monogenic diabetes." (PMID 37798422, 2023). "The use of 8 simple clinical features in the logistic regression model based MODY risk calculator distinguished the 3 common monogenic diabetes subtypes GCK, HNF1A, HNF4A collectively from Type 1 diabetes or Type 2 diabetes with a c-statistic of 0.98 and 0.95 respectively." (PMID 37794142, 2023). "Variants in GCK, HNF1A, and HNF4A genes are the three main causes of monogenic diabetes." (PMID 40225161, 2023). "Here, we show that polygenic burden also affects the impact of rare HNF1A variants in a functional domain that have functional implications but are not known to cause monogenic forms of diabetes, at least among individuals of European ancestry." (PMID 36216889, 2023). "Analysis of all the known monogenic diabetes genes did not identify a likely cause; however, she was noted to be heterozygous for a HNF1A p.(Thr537Arg) variant of uncertain significance." (PMID 36398453, 2023). "In this family-based study comparing relatives with and without the heterozygous HNF1A variant p.(Gly292fs), we show that although half of the variant carriers progress to overt diabetes by the age of 23 years, 13% are free of diabetes at the age of 50." (PMID 34951657, 2022). "We conducted a family-based multigenerational study by comparing heterozygous carriers of the HNF1A p.(Gly292fs) variant with the non-carrier relatives irrespective of diabetes status." (PMID 34951657, 2022). "We investigated associations between α1-3,4 fucosylation levels and either sex or age within individuals with diabetes without rare variants in the HNF1A gene." (PMID 34939081, 2022). "We show that diabetes risk is substantially lower in clinically unselected settings for HNF1A/HNF4A-MODY but not for GCK-MODY." (PMID 36257325, 2022). "When considering all previously analyzed 320 diabetes cases with and without variants in the HNF1A gene, a significant but weaker correlation with the correlation coefficient r = 0.68 was obtained." (PMID 34939081, 2022). "Moreover, lower expression of HNF1A in pancreatic β cells was observed in mice and humans with diabetes, as well as in a pancreatic carcinoma cell line; it is possible that HNF1A expression is partially regulated by CpG methylation of the HNF1A gene." (PMID 35741825, 2022).
diabetes (continued). "HNF1α and HNF1β form homodimers and heterodimers to regulate gene transcription in liver, pancreas, and kidney and HNF1β mutations in MODY5 patients leads to severe diabetes, in part due to the fundamental role of HNF1β in early pancreatic morphogenesis." (PMID 35235779, 2022). "Some studies have found that diabetes accounts for approximately 30-40% of all HNF1A-MODY patients." (PMID 35299962, 2022). "The validity of the assay was tested on 1000 blood plasma samples from a diabetes cohort, which included diagnosed cases with and without rare variants in the HNF1A gene." (PMID 34939081, 2022). "Similarly, enhanced SGLT2 mRNA in diabetes is positively correlated to the activation of hepatocyte nuclear factor 1 alpha (HNF-1α)." (PMID 35663316, 2022). "Recently, four atypical cases of young CF patients were reported with hyperglycemia associated with mutations in the hepatocyte nuclear factor 1-alpha (HNF1A) (two siblings) and Glucokinase (GCK) (two single cases) genes responsible for the two more frequent forms of monogenic diabetes." (PMID 33810109, 2021). "Furthermore, a genomic test is performed by observing the gene encoding glucokinase, HNF1A, and HNF4A, which are associated with diabetes onset." (PMID 34204428, 2021). "Based on the presence and assessed disease-causality of HNF1A mutations, participants were divided in four groups: (likely) damaging (n = 18), (likely) benign (n = 8) and VUS (n = 5), and a group of no HNF1A mutation diabetes cases (n = 289)." (PMID 33765222, 2021). "Our mutational analysis of only GCK, HNF4α, HNF1α, and HNF1β genes is not sufficient to strictly confirm the susceptibility mutation in patients with an onset of diabetes at an early age." (PMID 34746319, 2021). "There was also a patient with a history of T1DM, T2DM, and HNF1A diabetes." (PMID 35002955, 2021). "In contrast to GCK-MODY, there is impairment of first and second-phase insulin secretion in individuals with HNF1A mutations, resulting more often in overt diabetes as opposed to the mild hyperglycemia seen in the first." (PMID 32528556, 2020). "The finding of 8% of ABCC8 mutations in 85 individuals with sulfonylurea-sensitive diabetes, negative for HNF1A and HNF4A mutation, and without neonatal onset illustrate this principle." (PMID 32528556, 2020). "CHI within the neonatal period and evolution to diabetes later in life has been reported in individuals with heterozygous inactivating mutations in the hepatocyte nuclear factor 4A and 1A genes (HNF4A and HNF1A) and dominant mutations in ABCC8 genes in a very limited number of cases." (PMID 29739729, 2019). "It has been reported that Hnf1a could transactivate the insulin I gene and that Hnf1a knockout mice developed non-insulin-dependent diabetes mellitus." (PMID 31333621, 2019). "The HNF1A gene has been identified in both monogenic and polygenetic diabetes." (PMID 31109344, 2019). "The HNF1A gene contributes to the pathogenesis of Type 2 diabetes mellitus (T2DM)." (PMID 31109344, 2019). "However, the clinical phenotype of HNF1A-MODY diabetes varies considerably, and studies examining correlations between genotype and phenotype are still rare." (PMID 31739614, 2019). "HNF1A gene p.I27L TT genotype was increased in diabetes (TT vs. GG, OR = 1.71, 95% CI: [1." (PMID 31109344, 2019). "Similar to our report, paternal diabetes was higher in HNF1A gene SNP carriers." (PMID 31109344, 2019). "HNF1A variants cause autosomal dominant maturity-onset diabetes of the young (MODY; MIM: 600496), a form of monogenic diabetes that is often misdiagnosed as type 1 or type 2 diabetes, as was the case in this participant, who was incorrectly diagnosed with type 2 diabetes in her early 30s." (PMID 30487145, 2018). "Another example is the low-frequency E508K variant in HNF1A, which in the Latino population appears to increase risk of type 2 diabetes rather than causing monogenic diabetes." (PMID 30377832, 2018).
diabetes (continued). "Thus, our findings support that the E3 SUMO ligase PIASγ regulates HNF-1A SUMOylation with functional implications, representing new targets for drug development and precision medicine in diabetes." (PMID 30143652, 2018). "HNF1A plays a critical role in the normal functionality of the endocrine pancreas, with hereditary inactivating mutations in the gene and promoter region resulting in MODY3, an autosomal dominant form of diabetes resulting from β cell insufficiency." (PMID 30074477, 2018). "In this study 13 probands and family members out of 477 individuals with C-peptide positive and beta cell antibody negative diabetes, diagnosed before 45 years of age, had a rare HNF1A allelic variant." (PMID 29666556, 2018). "In addition, heterozygous protein truncating mutations were detected in the GCK, HNF1A, and HNF1B genes in seven individuals with diabetes." (PMID 29207974, 2017). "In particular, mutations in the HNF1A expressed in pancreatic cells lead to β-cell dysfunction, causing diabetes mellitus (MODY3); moreover, individuals carrying HNF1A mutations represent approximately 2% of overall diabetes cases." (PMID 28410371, 2017). "Nevertheless, the nature of the role of HNF1A in LADA is unclear, although any gene compromising insulin secretory function could predispose to diabetes." (PMID 28438156, 2017). "Of note, in our study, the HNF1A mutation-carrier identified among patients with a clinical diagnosis of T1DM was indeed negative for diabetes in his families." (PMID 26942212, 2016). "Pterin-4-alpha-carbinolamine dehydratase (PCBD1) is a novel protein that acts as a cofactor for HNF1A-dependent transcription protein, and it is reported that PCBD1 mutations cause early-onset nonautoimmune diabetes with features similar to dominantly inherited HNF1A-diabetes." (PMID 26901059, 2016). "However, given a lack of GAD65/IA2 antibodies and a maternal family history of diabetes for three generations, she was referred for HNF1A and HNF4A genetic testing." (PMID 25015100, 2014). "In addition, features of HNF1A and HNF4A mutation carriers tend to overlap with type 1 diabetes, type 2 diabetes and other monogenic forms of diabetes." (PMID 23803251, 2013). "Consequently, patients misdiagnosed as type 1 diabetes and treated with insulin can be switched to oral SU therapy once the genetic diagnosis of HNF1A diabetes is made." (PMID 23766565, 2013). "It is the role of HNF1A in liver which provides the greatest potential for urinary and/or plasma biomarkers, which could aid the differentiation from other forms of diabetes." (PMID 22859960, 2012). "Data were used to build a valid partial least squares discriminate analysis (PLS-DA) model where HNF1A-MODY subjects could be separated from the other diabetes subtypes." (PMID 22859960, 2012). "Unlike these common HNF1A variants, the diabetes phenotype that emerged in S319 allele carriers was non-MODY type 2 diabetes." (PMID 21208426, 2011). "Our results support that an environmental variable, cigarette smoking, may influence the development of the diabetes phenotype in the HNF1A G319S carriers." (PMID 21208426, 2011). "Based on these findings, the authors argued that variation in genes including HNF1A may have subsequent impact on vascular disease and diabetes influenced or marked by circulating CRP concentrations." (PMID 20716378, 2010). "CRP levels were lower in S319 allele carriers of the HNF1A gene compared to non-carriers among individuals without diabetes, but this difference was not present among those with diabetes, who uniformly had elevated CRP levels." (PMID 20716378, 2010). "In summary, CRP levels were lower in HNF1A S319 allele carriers compared to non-carriers among Aboriginal Canadians without diabetes, but this difference was not present among those with prevalent type 2 diabetes, a group with markedly elevated CRP levels." (PMID 20716378, 2010).
diabetes (continued). "As opposed to mice with homozygous Hnf1a mutations, which develop diabetes, this model has no documented in vitro or in vivo metabolic disturbances." (PMID 20523905, 2010). "The current study provides evidence that variation in HNF1A is associated with variation in CRP in diabetes-free individuals (although not in those with diabetes) in populations other than European Caucasians." (PMID 20716378, 2010). "eighteen LOADDM (age at onset > 40 y.o.; diabetes in 3 contiguous generations, uniparental lineage) along with 48 CT2DM patients and 42 normoglycemic controls (N group) have been evaluated for cardiovascular risk factors and SNPs of HNF1A." (PMID 19490620, 2009). "Hnf1α (Hepatocyte nuclear factor 1α) is a homeodomain protein encoded by the gene implicated in MODY3 (Maturity-onset diabetes of the young 3), the most common form of human monogenic diabetes." (PMID 18497863, 2008). "We used mice lacking Hnf1α, a transcription factor gene that is mutated in an inherited form of diabetes." (PMID 18497863, 2008). "On the other hand, it is not clear whether SGLT2i can be safely used in HNF1A-diabetes, which features insulin deficiency and already reduced expression of SGLT2 and glucosuria." (PMID 39025920, 2024). "Also, follow-up of the father regarding diabetes status in the years to come might reveal pathogenicity with a lower penetrance, and if the proband has type 1 diabetes exclusively or double diabetes (HNF1A-MODY and type 1 diabetes)." (PMID 37798422, 2023). "Consistent with our hypothesis, urinary E1S was significantly higher in the MODY3 group as compared to both non-diabetes and non-MODY3 diabetes patients, confirming that more E1S is excreted from the kidneys of MODY3 patients harboring HNF1A loss-of-function mutations." (PMID 37137894, 2023). "Finally, the relevance of any findings may extend beyond HNF1A-MODY to more common forms of diabetes." (PMID 36104811, 2022). "Our data suggest that intensive close monitoring of the onset of diabetes may not be necessary for people with incidentally identified pathogenic variants in HNF1A and HNF4A due to a substantially lower risk of diabetes." (PMID 36257325, 2022). "The remaining HNF1α mutation carriers were not diagnosed with diabetes before the follow-up period." (PMID 35299962, 2022). "Since HNF1A is a transcription factor, variation in its target genes might affect its binding affinity, and thereby influence target gene expression and ultimately the age at diabetes onset." (PMID 36104811, 2022). "A similar lack of GLUT2 expression observed in the HNF1A P291fsinsC mutant suggests that impaired glucose uptake capacity may be common amongst diabetes patients whose β cells harbor various HNF1A gene mutations." (PMID 34035238, 2021). "The most striking features of HNF1α-/HNF4α-MODY are that they result in a reduced insulin secretory response to glucose but marked sensitivity to low-dose sulfonylureas and cause progressive pancreatic β-cell dysfunction and increasing hyperglycemia that leads to diabetes in early adult life." (PMID 34746319, 2021). "Mutations in the HNF1α gene leads to maturity-onset diabetes of the young type 3 (MODY3), the most common form of MODY, suggesting that NKX6.1 defect may be associated with diabetes development by controlling the expression of MODY3 gene." (PMID 33121533, 2020). "This is the first study to investigate the association between HNF1A gene SNPs rs1169288 (encoding HNF1A p.Ile27Leu), rs1800574 (encoding HNF1A p.Ala98Val) and rs2464196 (encoding HNF1A p.Ser486Asn), and having early-onset, MODY-like diabetes in the Turkish population." (PMID 31109344, 2019). "HNF1A gene p.I27L SNP might contribute to age at diabetes diagnosis and family inheritance." (PMID 31109344, 2019). "The HNF1A gene p.I27L SNP might contribute to age at diabetes diagnosis and family inheritance." (PMID 31109344, 2019).
diabetes (continued). "Thus, in patients with HNF1A/HNF4A mutation, diabetes may present later than before traditionally defined 25 years of age." (PMID 30013516, 2018). "Thus, in diabetes, importin-α1 upregulation may exist as an adaptation to increases in extracellular glucose levels, contributing to enhanced HNF-1α transport into the nucleus and resulting in SGLT2 expression upregulation." (PMID 29717156, 2018). "The participant reported that she had previously tried a sulphonylurea medication to manage her diabetes but was taken off of the medication because of significant hypoglycemia, which we hypothesize may be due to the sensitivity of HNF1A diabetics to sulphonylureas." (PMID 30487145, 2018). "This suggests that the reduced expression of Slc2a2 may not necessarily be the limiting step that leads to diabetes in Hnf1a deficiency." (PMID 27667715, 2016). "However, most HNF1A mutation-carriers are initially misdiagnosed with type 1 (T1DM) or type 2 (T2DM) diabetes mellitus; hence, they often receive nonoptimal treatment." (PMID 26942212, 2016). "Comparison of bacterial profiles between patients with HNF1A-MODY and individuals with mutation in HNF1A gene without clinical diabetes could be significant." (PMID 27807544, 2016). "The aim of this current study was to obtain proof-of-concept that miR-224 and miR-103 are detectable in the urine of HNF1A-MODY mutation carriers, and to determine whether these diabetes-associated miRNA are also elevated in the urine of patients with T1DM and T2DM." (PMID 26110317, 2015). "Furthermore, a urinary c-peptide to creatinine ratio appears useful in distinguishing HNF1A/4A monogenic diabetes from type 1 diabetes when diabetes has been present for many years given that C-peptide progressively declines in type 1 diabetes but is retained in HNF1A/4A monogenic diabetes." (PMID 23766565, 2013). "HNF1A-MODY, the most common monogenic diabetes, exhibits progressive β cell dysfunction, but existing mouse models fail to recapitulate human disease progression, limiting understanding of pathogenic mechanisms." (PMID 42100870, 2026). "Similar to HNF1A-MODY, patients with HNF4A-MODY typically exhibit signs and symptoms of diabetes that develop gradually during childhood or young adulthood." (PMID 40149950, 2025). "Pregnancy outcomes in patients with subtypes of monogenic diabetes: GCK-hyperglycemia and HNF1A were comparable and generally favorable." (PMID 41409604, 2025). "Genetic diversity was limited to a few subtypes, with over-representation of HNF1A-MODY, meaning the results cannot be extrapolated to all forms of monogenic diabetes." (PMID 41262822, 2025). "Our prediction model focuses on detecting common MODY subtypes (GCK‐, HNF1A‐, HNF4A‐ and HNF1B‐MODY), which account for over 80% of monogenic diabetes reported in Chinese." (PMID 40966384, 2025). "Results revealed altered hepatic HNF-1α expression, thereby identifying HNF-1α as a promising molecular target for the development of future therapies aimed at preventing liver dysfunction and, consequently, may open new avenues for ameliorating diabetes and related severe metabolic conditions." (PMID 41614817, 2025). "In a multicenter study, including 169 pediatric patients with monogenic diabetes, GCK-MODY was identified as the most common subtype, accounting for 59.2% of cases, whereas HNF1A-MODY and HNF4A-MODY were detected in 18.3% and 1.2% of patients, respectively." (PMID 41367630, 2025). "MD subtypes are many but most patients bear defects in four of the Maturity Onset Diabetes of the Young (MODY) genes: GCK, HNF1A, HNF4A, HNF1B." (PMID 40244428, 2025). "The diagnosis of monogenic diabetes was known in approximately two-thirds of the women – for GCK-hyperglycemia - 9 women, and HNF1A-MD - 9 women." (PMID 41409604, 2025).